IL37 (interleukin 37)
Diseases named in the same sentence as IL37 in open-access papers (continued):
Sharing a sentence is not in itself a finding about the gene and the disease.
Obesity (continued). "This indicates that IL-37 may play an important anti-inflammatory role in obesity-induced inflammation and insulin resistance in both mice and humans and may serve as a potential target for the treatment of obesity, insulin resistance, and type 2 diabetes." (PMID 29805973, 2018). "IL-37 production has been reported to be low and it is mainly induced and detected upon pro-inflammatory stimuli, such as LPS or others that would accumulate during the development of obesity." (PMID 30072596, 2018). "Since IL-37 ameliorates insulin resistance and obesity-induced inflammation, it will be important to address whether IL-1R8 is involved in these contexts, preserving glucose tolerance and insulin sensitivity and reducing inflammation in the adipose tissue." (PMID 27148268, 2016). "In addition, IL-37 ameliorated diet-induced insulin resistance and improved insulin sensitivity in IL-37tg mice compared with WT mice, indicating potential as a treatment for obesity and type 2 diabetes." (PMID 35741608, 2022). "Studies found that IL-37 may be closely related to obesity and insulin resistance." (PMID 29805973, 2018).
periodontitis (23 papers, 2018 to 2026). An acute or chronic inflammatory process that affects the tissues that surround and support the teeth. "In the present study, we analyzed the levels of IL-1β, and an anti-inflammatory cytokine IL-37 in the GCF samples of periodontitis patients before and after treatment, and their association with other clinical parameters." (PMID 31308830, 2019). "Overall, these results from human gingival tissues further suggest the strong association between IL-37 and periodontitis." (PMID 30206230, 2018). "In the murine periodontitis model, IL-37 inhibits bone loss and inflammatory cell infiltrate." (PMID 30206230, 2018). "In addition, a recent study suggested that some IgG+ plasma cells could produce the anti-inflammatory cytokines IL-35 and IL-37 to regulate alveolar bone loss in periodontitis." (PMID 36072904, 2022). "Plasma cells are the main source of the anti-inflammatory factors IL-35 and IL-37 in the gingival tissues of patients with periodontitis." (PMID 41592028, 2026). "Our conclusion is based on the high number and intense staining of the IL-37-positive producer cells in periodontitis tissue samples and LPS treated epithelial cells." (PMID 40281482, 2025). "The number of IL-37 expressing cells was similar in patients with periodontitis and healthy controls in the superficial epithelial layer." (PMID 40281482, 2025). "The discovery of IL-35-producing plasma cell subsets—such as PIL-37 and PIL-35/IL-37—adds to the growing understanding of immune cell plasticity in chronic periodontitis." (PMID 40869939, 2025). "In periodontitis-affected tissues, IL-37 expression extends beyond the epithelial layer into the underlying connective tissue, suggesting an altered regulatory role in response to inflammation." (PMID 40281482, 2025). "Immunohistochemistry localized IL-37 in gingival tissues from periodontitis patients and healthy controls (N = 10)." (PMID 40281482, 2025). "The common finding in all periodontitis samples was that IL-37 expressing cells showed increasing staining intensity in periodontitis samples compared to the healthy group." (PMID 40281482, 2025). "The functional variant rs2723183 was predicted to affect m6A methylation and IL-37 mRNA expression, as well as alter regulatory motif binding, indicating it was involvement in the pathogenesis of periodontitis." (PMID 41444670, 2025). "In contrast, cells expressing IL-37 showed higher frequency in the basal epithelial cell layer in periodontitis samples compared with healthy samples." (PMID 40281482, 2025). "In this regard, higher IL-37 expression was found in both the epithelial layer and connective tissue layer of gingival tissue samples from periodontitis patients." (PMID 40281482, 2025). "Plasma cells, differentiated from B lymphocytes, are the dominant B cell type in periodontitis and regulate alveolar bone resorption via IL-35 and IL-37 production." (PMID 40612110, 2025). "IL-37 prevents the progression of periodontitis by suppressing NLRP3 inflammasome activation and mediating M1/M2 macrophage polarization." (PMID 38800469, 2024). "The present study analyzes the clinical periodontal parameters and the IL-1β and IL-37 levels in the GCF in generalized aggressive periodontitis patients before and after treatment with SRP and with or without additional diode or Er,Cr:YSGG laser therapy." (PMID 31308830, 2019). "IL-37 probably increased due to elevated IL-1β cytokine levels in the inflamed periodontal tissues prior to aggressive periodontitis treatment." (PMID 31308830, 2019). "The levels of proinflammatory cytokine IL-1β, which plays a role in the pathogenesis of aggressive periodontitis, were shown to be positively correlated with the IL-37 levels." (PMID 31308830, 2019). "We further delineated the major groups of cells producing IL-37 in periodontitis gingival tissue by IHC and found IL-37 mainly expressed by gingival epithelial cells and infiltrated immune cells in connective tissue." (PMID 30206230, 2018).
periodontitis (continued). "Furthermore, immunohistochemistry revealed increased IL-37 expression in periodontitis tissues, both in epithelial cells and connective tissue." (PMID 40281482, 2025). "The more extensive recruitment of IL-37 in periodontitis might indicate the extra burden posed by periodontal inflammation." (PMID 40281482, 2025). "Limited studies have focused on the role of IL-37 in periodontitis, yielding diverse conclusions." (PMID 40281482, 2025). "Progranulin and IL‐37 can promote the high expression of IL‐10 in M2 macrophages, which can alleviate the progression of periodontitis in mice, suggesting that the remission of periodontitis is related to IL‐10." (PMID 41181974, 2025). "Spearman's correlation analysis was conducted to examine the relationships between variables.In saliva samples, NLRP3, caspase-1, IL-1β, and IL-18 were the highest in the periodontitis group (p < 0.005), while IL-37 was highest in the healthy group (p < 0.005)." (PMID 40267956, 2025). "In this work, therefore, we hypothesize that IL-37, being a blocker of IL-1, one of the main inflammatory cytokines in the pathogenesis of periodontitis, may be of help in the therapy of this common disease." (PMID 36362030, 2022). "IL-37-producing plasma cells (CD138+CD38+PIL-37) expressing IL-37 and IL-37/IL-35-coproducing plasma cells (CD138+CD38+PIL-35/IL-37) expressing both of them are denoted as IgG+ plasma cells, and reduce periodontitis by suppressing the loss of alveolar bone by blocking osteoclast formation." (PMID 34248996, 2021). "However, further studies are needed to elucidate the regulatory mechanisms of IL-37 in the pathogenesis of generalized aggressive periodontitis." (PMID 31308830, 2019). "We additionally determined IL-37 expression and localization by immunohistochemistry (IHC); our results indicated enhanced IL-37 positive staining in periodontitis gingival tissue, especially in the infiltrate within the connective tissue and within the epithelium." (PMID 30206230, 2018). "Thus, IL-37 and IL-35 may represent a potential therapeutic agent in the treatment of periodontitis." (PMID 34248996, 2021). "Therefore, IL-37 may be used as a novel treatment biomarker for generalized aggressive periodontitis diagnosis." (PMID 31308830, 2019). "In another study, clinical data demonstrated a decrease in IL-37 levels in the gingival crevicular fluid samples of periodontitis patients but failed to differentiate healthy patients from those with periodontal disease." (PMID 40281482, 2025). "Similarly, in our study, GCF IL-37 levels in samples from inflamed areas in aggressive periodontitis patients were found to be high before treatment, while a significant decrease was observed in the level of GCF IL-37 after treatment." (PMID 31308830, 2019).
lung cancer (21 papers, 2016 to 2025). A malignant neoplasm involving the lung. "However, there are clearly several unresolved questions regarding the molecular mechanisms underlying this differential expression profile, such as whether aberrant IL-37 regulation is a cause or consequence of lung cancer development and progression." (PMID 36551790, 2022). "IL-37 also exerts anti-tumor effects by regulating the m6A modification activity of lung cancer cells and inhibiting the Wnt5a/5b pathway." (PMID 41293155, 2025). "Reduced tumour size was observed in nude mice recipients of IL-37 transgenic human lung cancer cells compared to those with mock transgenic cells." (PMID 40191189, 2025). "In contrast, IL‐37 upregulates METTL14 expression in lung cancer, thereby enhancing CD8+ T‐cell infiltration." (PMID 41316520, 2025). "From a mechanistic perspective, an animal model of lung cancer has been employed to explore the impact of IL-37 on tumour growth." (PMID 40191189, 2025). "This review summarizes the effects of IL-37 on respiratory diseases, including bronchial asthma, coronavirus disease of 2019 (COVID-19), tuberculosis, fungus, lung cancer, and pulmonary fibrosis." (PMID 41293155, 2025). "In vitro investigations have demonstrated that exogenous IL-37 inhibits lung cancer cell proliferation and migration, while suppressing epithelial-to-mesenchymal transition via the STAT3 signalling pathway." (PMID 40191189, 2025). "Depletion of the IL-37 gene in two distinct lung cancer cell lines (H460 and A549) suppressed MARCO expression and diminished IL-10 production in co-cultured macrophages." (PMID 38983267, 2024). "The m6A modification-related inflammatory cytokine interleukin 37 (IL-37) has received extensive attention for the treatment of lung cancer." (PMID 36553648, 2022). "It is of note that IL-37 expression exhibits a lung cancer stage-specific pattern: there is a trend of steady decline in its levels from earlier to later stages." (PMID 36551790, 2022). "Analysis revealed that the IL-37 expression pattern significantly differs in various types of human cancers (one-way ANOVA p < 0.0001), whereas among the 17 types examined, lung cancer exhibited the highest IL-37 mRNA levels (mean ± SD: 6.5 ± 31.88, n = 994)." (PMID 36551790, 2022). "For example, lung cancer cells were found to promote M2 polarization through the release of IL-37, leading to macrophage expression of MARCO (macrophage receptor with collagenous structure) and the induction of tumor-promoting phenotypes." (PMID 33924237, 2021). "We also showed the expression of m6A writers METTL3, METTL14, and WTAP and erasers ALKBH5 and FTO in A549 cells and lung cancer tissues after the treatment of IL-37." (PMID 33489865, 2020). "We also tested the expression of m6A writers METTL3, METTL14, and WTAP and of erasers ALKBH5 and FTO after the treatment of IL-37 in A549 cells and lung cancer tissues." (PMID 33489865, 2020). "We conclude that IL-37 suppresses tumor growth through regulation of RNA m6A methylation in lung cancer cells." (PMID 33489865, 2020). "To explore the protective role of IL-37 in lung cancer, we performed an m6A-specific RNA immunoprecipitation assay coupled with high throughput sequencing (MeRIP-seq)." (PMID 33489865, 2020). "To address the function of IL-37 in lung cancer, we first evaluated IL-37 expression in the human NSCLC tissues; IL-37 function was assessed in vitro in IL-37 over-expressing lung cancer cell lines, and in vivo in a xenografted lung tumor model." (PMID 26791086, 2016). "A high level of IL-37 correlates with a lower level of VEGF in lung cancer cell lines and reduced microvessel density in NSCLC patients." (PMID 27445423, 2016). "Our results show that IL-37 plays an inhibitory role in lung cancer development, possibly through inhibiting tumor angiogenesis." (PMID 26791086, 2016). "Together, our findings suggest that IL-37 suppresses lung cancer development possibly through inhibiting tumor angiogenesis." (PMID 26791086, 2016).
lung cancer (continued). "To investigate the role of IL-37 in tumorigenesis, we stably transfected lung cancer cell line H1299 cells with IL-37 cDNA and empty vector as control (mock transfectant)." (PMID 26791086, 2016). "Our findings demonstrate a protective role for IL-37 in lung cancer development, possibly through inhibiting tumor angiogenesis." (PMID 26791086, 2016). "However, inhibiting IL-37 significantly enhanced the death of AEC (A549 cells) derived from human lung cancer." (PMID 41293155, 2025). "In contrast, IL-37 expression was negatively correlated with the percentage (%) of infiltrating MDSCs, which are pivotal immunosuppressive partners and key targets for immunotherapy in lung cancer." (PMID 36551790, 2022). "Indeed, antibody-mediated blockade of MARCO and IL-37R, or CRISPR knockout of IL-37 in lung cancer cells, altered TAM phenotypes, resulting in reduced activity of regulatory T cells and enhanced cytotoxic function of both NK and T cells." (PMID 33924237, 2021). "In a recent study, IL-37 inhibits tumor growth by regulating RNA m6A methylation in lung cancer cells, may downregulate the proliferation by inhibiting Wnt5a/5b pathway in lung cancer cells." (PMID 34248996, 2021). "Moreover, we found that treatment of IL-37 in lung cancer cells induced widespread and dynamic RNA m6A methylation." (PMID 33489865, 2020). "Interleukin 37 (IL-37) plays a crucial protective role in lung cancer." (PMID 33489865, 2020). "After IL-37 was overexpressed in lung cancer cell line A549 cells, the overall methylation level of RNA increased significantly, suggesting that the inhibitory effect of IL-37 on the proliferation of lung adenocarcinoma cells may be caused by RNA methylation." (PMID 33489865, 2020). "Consequently, the observed gradual decrease in IL-37 expression during tumor progression and advanced lung cancer stages suggests that this anti-tumor effect could probably be attenuated." (PMID 36551790, 2022). "However, IL37 plays a protective role in most cancers, such as lung cancer and colorectal cancer." (PMID 34248843, 2021). "Recent findings suggest that the intracellular mature form of IL-37 can block the activation of Rac1 and its downstream signaling by binding to the Rac1 CAAX motif, thus suppressing the migratory behavior of lung cancer cells." (PMID 41293155, 2025). "Several studies have focused on the influence of IL-37 on NSCLC, which accounts for 80-85% of lung cancer with 5-year OS rate is <15% in the US and <10% in China." (PMID 37928545, 2023). "Recent interest in the role of interleukin-37 (IL-37) in NSCLC progression has emerged, with studies suggesting its potential to exert protective effects through various mechanisms, offering new avenues for lung cancer therapy." (PMID 41293155, 2025). "IL-37 markedly represses mouse primary AEC death induced by oxidative stress in a dose-dependent manner, while knockdown of IL-37 markedly promotes the death of human lung cancer cells derived from AEC (A549 cells)." (PMID 34248996, 2021). "Using immunohistochemical staining, we found that IL-37 was expressed in non-tumor tissues, which was down-regulated in lung cancer tissues." (PMID 26791086, 2016). "Overexpression of IL-37 exerted no direct effect on cell proliferation and apoptosis of H1299 lung cancer cells in vitro, but significantly inhibited tumor growth in a H1299 xenograft model in vivo." (PMID 26791086, 2016). "To confirm our findings of clinical, we constructed lung cancer cell line H1299 that overexpressed IL-37; we found that IL-37 did not directly inhibit cell growth of lung cancer cells in vitro." (PMID 26791086, 2016). "Previous studies suggested that IL-37 could inhibit the activation of the NF-κB and IL-6/STAT3 signaling pathway and suppressed the occurrence of the inflammatory response in Myasthenia Gravis (MG) by affecting Tfh and B cells, and in lung cancer by affecting A549 cells." (PMID 32733162, 2020).
lung cancer (continued). "Other cytokines that have not yet been shown to function as lung cancer biomarkers (TGF-β, IL-17, IL-32, IL-7, and IL-37) can play important roles in this disease, but further studies are required to determine whether they can act as biomarkers." (PMID 27445423, 2016).
myocardial infarction (21 papers, 2014 to 2025). Gross necrosis of the myocardium, as a result of interruption of the blood supply to the area, as in coronary thrombosis. "In mice with myocardial infarction, IL‐37 intervention significantly decreases cardiac macrophage infiltration." (PMID 40452816, 2025). "In a myocardial infarction model, we showed that treatment with IL-37 significantly alleviated cardiac dysfunction and fibrosis." (PMID 38790051, 2024). "Recently, our group revealed that IL-37 and Troponin I (TnI) treated DCs obtained a tolerogenic phenotype and alleviated cardiac remodeling after myocardial infarction." (PMID 34471467, 2021). "Recently, our group found that DCs treated with IL-37 plus troponin I alleviate cardiac remodeling after myocardial infarction." (PMID 31686988, 2019). "Of note, our previous experimental researches revealed that IL-37 plays a beneficial part in myocardial infarction and myocardial ischemia/reperfusion injury." (PMID 31686988, 2019). "The previous studies have shown that IL-37 increases substantially in peripheral blood of patients with acute myocardial infarction." (PMID 30728750, 2019). "Another study showed that IL-37 treatment can improve cardiac function through inhibiting the activation of NF-κB signaling pathway in a myocardial infarction model." (PMID 28781417, 2017). "Recent study revealed that IL‐37 level increased obviously in peripheral blood of acute myocardial infarction (MI) patients." (PMID 28548248, 2017). "Similarly, in a mouse model of myocardial infarction, the administration of IL37 was found to modulate macrophage polarization toward the M2 phenotype in the infarcted heart, resulting in a therapeutic effect on myocardial infarction." (PMID 39500733, 2024). "The expression level of IL-37 is known to be low under normal physiological conditions; however, the expression level of IL-37 is significantly upregulated in response to an inflammatory environment, such as in patients with acute myocardial infarction (AMI)." (PMID 37047468, 2023). "Similarly, recombinant IL-37 treatment in WT mice also provides protection in models of myocardial infarction." (PMID 30728750, 2019). "In animal models, the use of IL-37 has been beneficial for the treatment of myocardial infarction (MI), ischemia/reperfusion injury, and vascular calcification." (PMID 34199391, 2021). "In one study performed on mice models, IL-37 seemed to improve cardiac function if given after acute myocardial infarction (MI)." (PMID 29234571, 2017). "For example, IL-37 has been found to regulate macrophage programming through the YAP/NLRP3 pathway, indicating its therapeutic potential in myocardial infarction." (PMID 39121041, 2024). "A recent study reveals that IL-37 may improve the cardiac function in myocardial infarction (MI) mice via inhibition of the inflammatory NF-κB signaling pathway." (PMID 30728750, 2019). "However, the exact role of IL‐37 and IL‐37 plus troponin I (TnI)–treated dendritic cells (DCs) in ventricular remodeling after myocardial infarction (MI) remains elusive." (PMID 27919929, 2016). "However, the plasma levels of IL-37 in patients with acute coronary syndrome (ACS, including unstable angina pectoris and acute myocardial infarction) have yet to be investigated." (PMID 24733959, 2014).